GPX8 (glutathione peroxidase 8 (putative))
Description:
Acts as an endoplasmic reticulum (ER) thiol peroxidase that maintains ER redox homeostasis and protects the cytosol from ER-derived H(2)O(2). Functions in a redox relay with ERO1A, using ERO1A-generated H(2)O(2) to drive PDI oxidation, linking peroxide detoxification to productive disulfide formation. Modulates endoplasmic reticulum Ca(2+) levels mainly through SERCA pump activity and partially by influencing passive Ca(2+) leakage.
Synonyms: GPx-8; GSHPx-8; UNQ847; EPLA847
Tractability: Antibody: UniProt predicts a signal peptide or a membrane-spanning region; the Human Protein Atlas places it where antibodies can reach. PROTAC: ubiquitination databases record sites on it.
Gene: Protein-coding gene on chromosome 5 (55,160,167 to 55,167,297, forward strand). Ensembl gene ENSG00000164294.
Subcellular location: Endoplasmic reticulum membrane
Subcellular location (Human Protein Atlas): Cytosol; Plasma membrane; Actin filaments
Pathways (Reactome):
Cellular responses to stimuli: Detoxification of Reactive Oxygen Species
Gene Ontology:
Molecular function: peroxidase activity; protein binding; glutathione peroxidase activity; protein disulfide isomerase activity
Biological process: cellular response to oxidative stress; cellular oxidant detoxification; response to oxidative stress
Cellular component: endoplasmic reticulum membrane; endoplasmic reticulum lumen
Genetic constraint (gnomAD): Loss-of-function variants: 7 observed, 12.25 expected, observed/expected ratio (o/e) 0.57, 90% interval 0.32 to 1.07. The upper end of that interval is the gene's LOEUF score, 1.07, which puts it in group 4 of 6, group 1 being the genes least tolerant of losing a copy. Missense variants: 186 observed, 207.69 expected, observed/expected ratio (o/e) 0.9, 90% interval 0.79 to 1.01. Synonymous variants: 79 observed, 80.56 expected, observed/expected ratio (o/e) 0.98, 90% interval 0.82 to 1.18.
Homologues: Orthologues: chimpanzee GPX8 (99% identical), macaque GPX8 (98% identical), rabbit GPX8 (89% identical), guinea pig GPX8 (83% identical), rat Gpx8 (83% identical), mouse Gpx8 (82% identical), pig GPX8 (68% identical), tropical clawed frog gpx8 (68% identical), dog GPX8 (66% identical), zebrafish gpx8 (63% identical), Caenorhabditis elegans gpx-2 (26% identical), Caenorhabditis elegans gpx-3 (22% identical), and 3 more. Paralogues in human: GPX7 (45% identical), GPX5 (29% identical), GPX4 (28% identical), GPX1 (27% identical), GPX2 (25% identical), GPX6 (25% identical), GPX3 (25% identical).
Diseases named in the same sentence as GPX8 in open-access papers:
GPX8 is named in the same sentence as 48 diseases in open-access papers, as found by Europe PMC text mining. Sharing a sentence is not in itself a finding about the gene and the disease. The quoted sentences say what the papers report.
breast carcinoma (13 papers, 2020 to 2025). "In contrast to the closely related GPX7, which has been posited as a tumor suppressor, emerging evidence has implicated GPX8 as a pro-tumorigenic factor in various cancers such as gastric, lung, and breast cancer." (PMID 36750850, 2023). "Another report had demonstrated the GPX8 was up-regulated in breast cancer and associated with epithelial-mesenchymal transition." (PMID 35402257, 2022). "Moreover, high expression of GPX8 is closely associated with poor prognosis in the patients with gastric cancer and promotes the progression of breast cancer and esophageal squamous cell carcinoma." (PMID 35978854, 2022). "Recent studies have shown that GPX8 can maintain the invasive mesenchymal-like phenotype of breast cancer cells through the IL-6/STAT3 axis." (PMID 38515109, 2024). "GPx8 is also part of the GPX8/IL-6/STAT3 axis that helps to suppress the progression of an aggressive type of breast cancer." (PMID 39796732, 2024). "Coincidentally, a study by Khatib has reported that GPX8 expression is crucial for maintaining the EMT phenotype in breast cancer cells." (PMID 38515109, 2024). "In separate studies, GPX8-KO suppressed IL6-STAT3 pathway in breast cancer cells, and IL6-STAT3 was shown to regulate NNMT expression." (PMID 36750850, 2023). "The GPX8/IL-6/STAT3 axis has been shown to maintain an aggressive breast cancer phenotype, and GPX8 itself mediates the proliferation and migration of GBM cells." (PMID 37795080, 2023). "The correlation between the high expression of GPx8 and a patient’s overall survival was found in those with gastric cancer and breast cancer." (PMID 35208621, 2022). "Intriguingly, it was reported that GPX8/IL6/STAT3 axis was important for maintaining aggressive phenotype in breast cancer." (PMID 35978854, 2022). "Scholars discovered the GPX8/IL-6/STAT3 axis as an essential pathway in regulating cell aggressiveness of breast cancer." (PMID 34284774, 2021). "Hence, further investigation is warranted to explore the involvement of GPX8 in angiogenesis within breast cancer." (PMID 38023262, 2023). "Several studies have reported the GPX8 could be correlated with the poor prognostic of Gastric Cancer and Breast Cancer." (PMID 35402257, 2022). "Furthermore, evidence has shown that GPX8 maintains an aggressive breast cancer phenotype by regulating the interleukin 6 (IL-6)/JAK/STAT3 signaling pathway, which is hyperactivated in many different malignancies and is generally linked to a poor prognosis." (PMID 35456975, 2022). "According to the hierarchical clustering analysis of 52 breast cancer cell lines, SOD2 and GPX8 genes were part of the mesenchymal gene signature and co-clustered with ZEB1, VIM, and SNAI2." (PMID 38172210, 2024). "Four GPXs family genes had the significant ability to distinguish breast cancer tissues from normal breast tissues, including GPX2, GPX3, GPX4 and GPX8." (PMID 32782436, 2020). "Glutathione peroxidase 8 (GPX8) has been demonstrated as crucial for maintaining the invasive phenotype in breast cancer; however, direct evidence linking GPX8 to breast cancer tumor angiogenesis is currently lacking." (PMID 38023262, 2023). "Recently, it was reported that lack of GPX8 suppresses the aggressive phenotype and stemness features in breast cancer cells." (PMID 35978854, 2022). "GPX8 showed no statistical difference between breast cancer tissues and normal tissues." (PMID 32782436, 2020).
glioma (10 papers, 2022 to 2026). A benign or malignant brain and spinal cord tumor that arises from glial cells (astrocytes, oligodendrocytes, ependymal cells). "GPX8 has shown diagnostic potential across various cancers besides cervical cancer, including glioma, kidney cancer, and stomach cancer." (PMID 38656879, 2024). "Recent studies have shown that GPX8 is associated with poor prognosis in various cancers, including gastric cancer, lung cancer, and glioma." (PMID 38515109, 2024). "The tumorigenic and immunogenic mechanisms associated with GPX8 warrant further validation through in vitro and in vivo experiments in glioma models." (PMID 37795080, 2023). "The pathogenic role of GPX8 in glioma was investigated in light of the exceptional performance of GPX8 in prognosis prediction." (PMID 37795080, 2023). "In primary gliomas, the GPX8 was associated with age, WHO grade, chemo, IDH mutation, histology, and 1p19q_codeletion." (PMID 36052280, 2022). "A literature search revealed that all of the selected overexpressed gene signatures were differentially expressed in gliomas and associated with either poor prognosis or low survival rates, except for the GPX8 gene." (PMID 35456975, 2022). "In short, results above supported that GPX8 is a potential diagnostic biomarker in glioma, including primary gliomas." (PMID 36052280, 2022). "However, further in vitro and in vivo investigations are necessary to validate the tumorigenic and immunogenic processes associated with GPX8 in gliomas." (PMID 37795080, 2023). "Collectively, these results suggest that the expression of GPX8 may be associated with the malignant progression of glioma." (PMID 36061208, 2022). "Moreover, the diagnostic value of GPX8 level in glioma was evaluated by exploring the receiver operating characteristic (ROC) curve." (PMID 36052280, 2022). "GPX8 acts as a key regulator of malignant phenotypes and radiosensitivity in glioma, positioning it as a promising therapeutic target to counteract both malignant progression and radioresistance." (PMID 42047740, 2026). "GPX8 has been recognized as a prognostic marker for cancers such as gastric cancer and primary glioma." (PMID 38515109, 2024). "CENPA, COL3A1, GRP65, SRPX2 and GPX8 were upregulated in glioma, while remaining genes were downregulated." (PMID 39620895, 2024). "The overall result revealed that GPx-8 was highly expressed in gliomas, as we have also described here." (PMID 37761814, 2023). "The results of the survival analysis using the CGGA databases revealed that GPX8 expression significantly affects prognosis in gliomas, including primary glioma." (PMID 36052280, 2022). "After showing the expression of GPX8 in gliomas, we are interested in GPX8 affecting the clinical outcome in glioma patients." (PMID 36061208, 2022). "Some research groups have proved that GPX8 knockdown results in the suppression of the proliferation, colony formation capacity, and migration of glioma cells." (PMID 36052280, 2022). "Subsequently, in order to further explore the function of GPX8, we obtained the mRNA expression data of GPX8 in glioma by accessing CGGA and TCGA databases." (PMID 36061208, 2022). "The Kaplan–Meier overall survival curve and Cox regression model were used to evaluate the prognostic value of GPX8 in glioma patients." (PMID 36061208, 2022). "Survival analysis results indicated that GPX8 is an independent prognostic factor for overall survival (OS) in all WHO-grade glioma patients." (PMID 36061208, 2022). "Further, by excluding recurrent and secondary gliomas, we solely analysed the correlation between GPX8 expression and the primary gliomas from CGGA by bioinformatics tools." (PMID 36052280, 2022). "According to results of univariate and multivariate analysis from CGGA using R studio, GPX8 is a valuable primary glioma prognostic indicator." (PMID 36052280, 2022). "In conclusion, GPX8 is a promising therapeutic target and meaningful prognostic biomarker of primary glioma." (PMID 36052280, 2022).
glioma (continued). "We next explored signaling pathways differentially expressed in patients with primary glioma as a function of GPX8 expression via GSEA." (PMID 36052280, 2022). "In brief, GPX8 is highly expressed in gliomas tissue, including primary, recurrent, and secondary gliomas." (PMID 36052280, 2022). "And GPX8 expression is significantly correlated with grade, IDH1/2 mutation, and 1p/19q codeletion in primary glioma from CGGA, which are favorable prognostic factors in glioma." (PMID 36052280, 2022). "In the present study, we firstly reported that decreased GPX8 expression led to increased cell apoptosis and cell arrest at the G1 stage using two glioma cell lines." (PMID 36052280, 2022). "In conclusion, the present study found that GPX8 is a favorable prognostic factor in primary glioma." (PMID 36052280, 2022). "Collectively, these results indicated that GPX8 is an independent prognostic factor for the OS of glioma patients." (PMID 36061208, 2022). "Though difference of RNA expression, survival, and ROC curve has been explored, further analysis is needed to do to confirm the potential role of GPX8 in gliomas." (PMID 36052280, 2022). "Above data suggested GPX8 plays an important role in the proliferation, cell cycle, apoptosis, migration, and colony formation capacity of glioma cells, which would be beneficial for disease development." (PMID 36052280, 2022). "So, next we focused on analysing the correlation of GPX8 with clinical characteristics of primary gliomas." (PMID 36052280, 2022). "Previously, several research groups explored the potential role of GPX8 in glioma patients, but their studies were only based on The Cancer Genome Atlas (TCGA)." (PMID 36052280, 2022). "GPX8 was overexpressed in high-grade gliomas and correlated with recurrence and poor survival." (PMID 42047740, 2026). "Knockdown of GPX8 suppressed the malignant biological behaviors of glioma cells." (PMID 42047740, 2026). "Genes like TMEM140 and GPX8 also play regulatory roles in gliomas." (PMID 38809929, 2024). "Although glutathione peroxidase 8 (GPX8) is intimately associated with carcinogenesis, its function in primary gliomas has not yet been thoroughly understood." (PMID 36052280, 2022). "The result revealed that GPX8 was highly expressed in gliomas." (PMID 36052280, 2022). "Noticeably, the mRNA expression of GPX8 was correlated with glioma WHO grade." (PMID 36061208, 2022). "Meanwhile, GPX8 function in gliomas was validated by in vitro experiments." (PMID 36052280, 2022). "In the present study, gene set enrichment analysis of GPX8 in primary glioma was performed." (PMID 36052280, 2022). "GPX8 could exert its carcinogenesis function in primary glioma accompanying the dysfunction of these coexpressed genes." (PMID 36052280, 2022). "We then explored the protein levels of GPX8 in glioma specimens." (PMID 36061208, 2022). "Moreover, the upregulation of GPX8 in both primary and recurrent gliomas affected the prognosis of patients." (PMID 36061208, 2022). "In vitro experiments were performed to validate the GPX8 function in gliomas." (PMID 36052280, 2022). "And the intervention of GPX8 in glioma tissue could be a promising therapy treatment for primary glioma treatments and other brain-related tumors." (PMID 36052280, 2022). "Our study shows that the mRNA and protein expression of GPX8 were upregulated in glioma." (PMID 36061208, 2022). "Moreover, the expression of GPX8 is significantly lower in normal tissue when compared to glioma tissue." (PMID 36052280, 2022). "Notably, the expression of GPX8 in HGG was significantly higher than that in LGG suggesting that malignant progression of glioma was correlated with GPX8 overexpression." (PMID 36061208, 2022). "Hence, we concluded that GPX8 is a meaningful predictive biomarker for primary glioma and a promising antiglioma therapeutic target." (PMID 36052280, 2022). "Notably, our findings identified GPX8 as a tumor promoter in gliomas." (PMID 37795080, 2023).
glioma (continued). "In addition, coexpressed genes of GPX8 in primary gliomas from CGGA were analysed." (PMID 36052280, 2022). "Moreover, in both of TCGA and CGGA datasets, GPX8 had higher expression in IDH-wildtype gliomas." (PMID 36061208, 2022). "The GPX8 expression in two glioma cell lines (U87MG and U118MG) was successfully knocked down by transfection of GPX8 siRNA, which was confirmed by WB." (PMID 36052280, 2022). "Our multivariate analysis showed that GPX8 was not a good prognostic indicator for the OS of all types of gliomas." (PMID 36052280, 2022). "Interestingly, high GPX8 expression is correlated positively with the hedgehog and kras signaling pathways and negatively with G2 checkpoint, apoptosis, reactive oxygen species (ROS) pathway, and interferon gamma pathway, which could be beneficial for the proliferation of glioma cells." (PMID 36052280, 2022). "Surprisingly, although GPX8 is proved to be a potential prognostic factor in glioma based on analysis of data from TCGA, our analysis results suggested that GPX8 is not a reliable prognostic factor in the analysis of mixed-type gliomas from CGGA." (PMID 36052280, 2022). "Our results favored that GPX8 is a promising prognostic factor mainly in primary glioma rather than in all types of gliomas." (PMID 36052280, 2022). "But they only used one glioma cell line and did not fully study the role of GPX8 expression in glioma cell apoptosis and cycle." (PMID 36052280, 2022).
gastric cancer (9 papers, 2022 to 2024). A primary or metastatic malignant neoplasm involving the stomach. "They found that aberrant GPX8 expression is associated with clinical features of gastric cancer, such as T stage, clinical stage, histological grade, residual tumor status, ethnicity, and patient survival." (PMID 35712475, 2022). "The immunohistochemical staining of GPX8 and survival analysis were performed in carcinoma tissue and adjacent tissues of 83 gastric cancer patients." (PMID 35712475, 2022). "The overexpression of GPX8 is significantly related to the clinical features of stomach cancer, such as histologic grade (G1 and G2 vs. G3, P = 0.003), pathologic stage (stage 1vs." (PMID 35712475, 2022). "FoxC1-induced transcriptional activation of GPX8 activates Wnt signaling and subsequent gastric cancer cell proliferation." (PMID 35456975, 2022). "Therefore, apart from the validation of GO analysis, the results of KEGG signaling analysis also showed that some signaling pathways such as AGE/RAGE, relaxin, and PI3K/AKT signaling pathways were involved in the functions of GPX8 in stomach cancer." (PMID 35712475, 2022). "had reported that the over-expression of GPX8 was observed in gastric cancer and could promote the malignant behavior of gastric cancer cells." (PMID 35402257, 2022). "In addition, GPX8, a member of the selenoproteome, is identified to promote cancer growth and progression in gastric cancer and non-small-cell lung cancer, while the role of GPX8 in LIHC is not well identified." (PMID 36398067, 2022). "A recent article also found that GPX8 can significantly predict prognosis in gastric cancer." (PMID 35712475, 2022). "In addition, we validated the correlation of the differential expression of GPX8 with clinical features and prognosis of gastric cancer patients by collecting clinical samples from hospitals." (PMID 35712475, 2022). "Increasing evidence has verified that GPX8 could be correlated with the poor prognostic of cancers and involved in diverse physiological processes and tumorigenesis, including gastric cancer, lung cancer and others." (PMID 35402257, 2022). "In gastric cancer, FOXC1 promotes cell proliferation by enhancing GPX8 transcription to activate Wnt signaling pathway." (PMID 39093497, 2024). "GPX8 is under the regulation of FOX1 transcription and facilitates the proliferation of gastric cancer cells by activating Wnt signaling pathway." (PMID 38656879, 2024).